EZH2 (enhancer of zeste 2 polycomb repressive complex 2 subunit)
Diseases named in the same sentence as EZH2 in open-access papers (continued):
Sharing a sentence is not in itself a finding about the gene and the disease.
melanoma (continued). "EZH2 is highly upregulated in various malignancies such as melanoma and plays a vital role in cell growth and proliferation; therefore, EH2 is highlighted as an anti-tumor treatment." (PMID 35163049, 2022). "Accordingly, pharmacological inhibition of EZH2 by GSK503 decreased melanoma progression in melanoma-bearing mice in vivo and doubled the survival time." (PMID 35163453, 2022). "The functional role of EZH2 in promoting melanoma metastasis has been well established, suggesting its potential contribution to miRNA-124a metastasis suppressive role reported here." (PMID 35480113, 2022). "EZH2 is induced in response to immunotherapy (IL-2 or anti-CTLA-4) in tumors developed upon grafting of B16F10 or NrasQ61K Ink4a-/- melanoma cells." (PMID 35432344, 2022). "EZH2 is an important driver of melanoma progression, and its increased activity leads to increased global H3K27me3." (PMID 35163453, 2022). "GSK343 and GSK503 as the selective EZH2 inhibitor have been shown to have therapeutic effects on pediatric glioma and melanoma 44-46." (PMID 35265199, 2022). "We identified a proportion of melanoma cases which harbored chromosomal amplifications and gains of regions including EZH2, SUZ12, and EED." (PMID 35223844, 2022). "Previous studies revealed that during melanoma progression, melanoma cells develop stem-cell like properties associated with the expression of SOX10, EZH2 transcription factors, EMT phenotypic switch regulators TWIST1/ZEB1, and the surface receptor CD172." (PMID 35269844, 2022). "The enhancer of zeste homolog 2 (EZH2) epigenetic modifier was found to be overexpressed in melanoma, resulting in tumor growth and spread by inhibiting tumor-suppressive genes." (PMID 35736636, 2022). "We also treated A375 human melanoma cells with the EZH2 inhibitor GSK-343 and verified decreased H3K27me3." (PMID 35223844, 2022). "In the pathogenesis of melanoma, another epigenetic component known as EZH2 seems to be highly involved." (PMID 36230787, 2022). "DNA methylation and enhancer of zeste homolog 2 (EZH2) activity were found to induce PD-1 resistance in melanoma by inhibiting IFN-γ transcription and the RAS and PI3K pathways’ subsequent functions." (PMID 36384676, 2022). "Increasing the level of both EZH2 and H3K27me3 have been reported in aggressive melanoma cell lines, whereby tumor suppressors RUNX3 (RUNX family transcription factor 3) and E-cadherin expression are suppressed via enabling senescence evasion." (PMID 36224606, 2022). "Among these are downstream and upstream combined inhibition of BRN2 by small molecules targeting its effectors EZH2 or its transcriptional regulator NFATc2, respectively, as observed in NFAT2+ EZH2+ melanoma cell lines." (PMID 36551603, 2022). "Collectively these studies show that EZH2 has an important role in the progression of melanoma, therefore its only known antagonist, KDM6A/B, is likely to be of equal importance and warrants exploration." (PMID 34220955, 2021). "A previous mouse model study demonstrated that inhibition of EZH2 using small-molecule inhibitors blocks melanoma growth and metastasis." (PMID 34771678, 2021). "FALEC predominantly resides in the nucleus, where it binds to EZH2, and this interaction in melanoma facilitates binding to p21 promoter and increases H3K27me3 modification, therefore repressing p21 transcription." (PMID 34638331, 2021). "Of interest, EZH2 is suggested to mediate resistance in BRAF mutant melanomas, and to cooperate with BRAF to maintain tumor progression." (PMID 34831002, 2021). "This provides further evidence that, in melanoma, EZH2 mediates miR-129-5p expression downstream of constitutive active BRAF signaling." (PMID 34063443, 2021). "We have now demonstrated that, in melanoma, EZH2 represses miR-129-5p, dependent on constitutive active BRAF signaling." (PMID 34063443, 2021). "EZH2 is upregulated in multiple cancers including breast, prostate, melanoma, and bladder cancer, and it has been targeted for inhibition." (PMID 34112092, 2021).
melanoma (continued). "The combination of the BRAF inhibitors vemurafenib and GSK2816126 revealed a more significant anticancer effect than vemurafenib monotherapy in melanoma models with both a BRAF V600E mutation and an EZH2 abnormality." (PMID 34001246, 2021). "Of note, in recent years a possible synergy between EZH2 inhibition and blocking the inhibitory checkpoint Cytotoxic T-Lymphocyte Associated Protein 4(CTLA-4) has been suggested, preventing melanoma expansion in resistant patients." (PMID 33467134, 2021). "In melanoma, an actionable axis linking NFATc2 to EZH2 was shown to control the EMT-like program of melanoma cells, while inhibition of EZH2 downregulated EMT-related gene expression." (PMID 34199763, 2021). "Other lncRNAs that contribute to gene repression in melanoma through direct interaction with EZH2 are CASC5, FALEC, HEIH, LNMAT1 and PVT1." (PMID 34638331, 2021). "EZH2 is an epigenetic-modifying histone methyltransferase, known to regulate melanoma growth and metastasis by silencing tumor suppressors and also induce resistance to immunotherapy." (PMID 33428680, 2021). "In melanoma, EZH2 suppresses the expression of ciliary biogenesis genes and drives the formation of metastatic melanoma with non-ciliated stem-like cells due to the increased activity of Wnt/β-catenin signaling." (PMID 34201019, 2021). "The involvement of EZH2 in this process was evidenced by the findings that increased EZH enhances WNT/β-catenin signaling in benign melanocytic cells, and inhibition of EZH2 with GSK503 induces cilia assembly in most melanoma cell lines." (PMID 34359832, 2021). "Here we identified miR-129-5p as a novel tumor suppressor in BRAF mutated melanoma, which expression is increased during response to BRAF inhibition, but repressed in an EZH2 dependent manner during activated BRAF signaling." (PMID 34063443, 2021). "The use of EZH2 inhibitors in melanoma cell lines demonstrated anti-tumor efficacy in both EZH2 wild-types and mutant forms." (PMID 34831002, 2021). "Here, we review the literature on G9a, its role in melanoma, and lessons from EZH2 inhibitor studies." (PMID 34691767, 2021). "Our analysis of publicly available Talantov melanoma datasets revealed that only EZH2, BRD7/9, BRD2/3/4, BRPF1, EHMT2, and KDM6B were significantly overexpressed at the mRNA level in patient melanoma tissue samples as compared to the normal skin samples." (PMID 34771678, 2021). "At the core of these critical contributors to tumor aggressiveness lies NFIB, a downstream target of c-Myc (SCLC) and an inducer of EZH2 (melanoma)." (PMID 34922631, 2021). "For example, transcription factors, such as MITF in melanoma have been proposed to drive dedifferentiation and invasion through epigenetic regulators, like the polycomb repressive complex 2 protein, enhancer of zeste homolog 2 (EZH2)." (PMID 34680938, 2021). "Colony formation assays showed that USP7 or EZH2 depletion hampered the colony formation of melanoma A375 cells, which was also rescued, to some extent, by knockdown of FOXO1." (PMID 33849069, 2021). "In B16 or RIM-3 melanoma cells, EZH2 inhibition resulted in upregulation of antigen presentation molecule expression via modulating H3K27me3 modification on promoter regions." (PMID 33403469, 2021). "Our findings support the emerging data that implicates the role of EZH2 histone methyltransferase in progression of melanoma and suppression of immune responses via various mechanisms including stabilization of the activated Treg cells." (PMID 33428680, 2021). "EZH2 inhibition together with anti-CTLA-4 has combinatory effects in melanoma and bladder cancer models." (PMID 33859645, 2021). "In an effort to better understand the biological function of EZH2 and to investigate its role in the development of cancer, we generated a human malignant melanoma A375 cell line stably expressing FLAG-EZH2." (PMID 33849069, 2021).
melanoma (continued). "In primary melanoma growth, it is clear that most cells are unciliated, and that EZH2 acts to suppress those genes." (PMID 34725363, 2021). "Another lncRNA that represses miR-200 family expression through EZH2-mediated binding to miR-200 promoter is plasmacytoma variant translocation 1 (PVT1), also upregulated in melanoma." (PMID 34638331, 2021). "The results of our study demonstrate that EZH2 dependent repression of miR-129-5p is solved by BRAFi/MEKi treatment thereby modulating BRAFi resistance and melanoma progression via targeting SOX4." (PMID 34063443, 2021). "The reactivation of tumor suppressors was correlated to increased survival confirming that EZH2-mediated epigenetic repression has a major role in advanced melanoma progression." (PMID 32850962, 2020). "Mechanistically, ILF3‐AS1 promoted melanoma cell proliferation, migration and invasion via repressing miR‐200b/a/429 expression by promoting the binding of EZH2 to their promoter." (PMID 31588640, 2020). "Our data and another histopathological study indicate a low expression (less than 20%) of EZH2 in melanoma assessed by IHC." (PMID 32041674, 2020). "Collectively, our investigation displayed that the silencing of lncRNA GAS5 and CDKN1C or elevation of EZH2, accelerated the viability of melanoma cells while suppressed oxidative stress and apoptosis of melanoma cells." (PMID 32308561, 2020). "The results provided strong evidence for the importance of KDM6A and EZH2 in the improved survival of females from melanoma." (PMID 32731355, 2020). "Along this line, our recent study identified immune-suppressive gene signatures in a subset of melanoma cell lines resistant to EZH2 inhibitors." (PMID 32731355, 2020). "It will be interesting to study in what extent MHC-I expression in melanoma is dependent on EZH2 activity as subunit of the PRC2 to enable immune evasion." (PMID 32041674, 2020). "EZH2 overexpression has been evidenced to play a significant role in stimulating melanoma progression." (PMID 32308561, 2020). "Using RNA sequencing (RNAseq) data from TCGA, it has been shown that EZH2 high expressing melanoma patients show shorter overall survival as compared with those of the EZH2 low-group." (PMID 32041674, 2020). "There were some differences in terms of the disease course and the mechanisms by which EZH2 promoted melanoma initiation and progression in the different studies." (PMID 33024276, 2020). "Activation of Ezh2 in the same model re-established the immunogenicity of the tumor and inhibited melanoma growth." (PMID 32344837, 2020). "Multiple datasets, spanning different modes of investigations, will be critical for a comprehensive understanding of H3K27me3 or EZH2 expression in melanoma." (PMID 32041674, 2020). "In melanoma, the EZH2 locus is amplified in 58.3% of melanoma samples from The Cancer Genome Atlas (TCGA) and EZH2 copy-number gains were associated with enhanced EZH2 transcription compared with samples with normal or loss of EZH2 copy numbers." (PMID 32041674, 2020). "In the immunotherapy using anti-CTLA-4 or IL-2 in mice, the production of tumor necrosis factor-a (TNF-a) in tumor cells and the accumulation of T cells led to an increase in EZH2 expression in melanoma cells." (PMID 32859239, 2020). "One study showed that conditional Ezh2 ablation or inhibition with the EZH2 inhibitor GSK305 prevented melanoma progression in Tyr: NRASQ61KInk4a−/− mice." (PMID 33024276, 2020). "EZH2 mutation (EZH2Y646) is observed in 3% of human melanomas, and focal amplification of EZH2 was noted in 15 of 262 (5.7%) cases of melanoma in TCGA." (PMID 33024276, 2020). "H3K27me3 and EZH2 expressing melanoma cells were more frequently found at the invasion front (IF) (29/44 samples) than in the inner tumor mass (21/44 samples)." (PMID 32041674, 2020).
melanoma (continued). "Therefore, immunohistochemically evaluation of H3K27me3 and EZH2 expression in melanoma and their association with immune cell infiltrates might be a suitable method to better understand EZH2-induced immune suppression and the potential role as predictive markers." (PMID 32041674, 2020). "Gain-of-function mutations in EZH2 have been reported in not only GCB-DLBCL, but also in other cancer types, including follicular lymphoma and melanoma." (PMID 32906688, 2020). "Another histone methyltransferase involved in melanoma is enhancer of zeste homolog 2 (EZH2), the catalytic subunit of the polycomb repressive complex 2 (PRC2) catalyzing trimethylation of lysine 27 on histone 3 subsequently repressing transcription." (PMID 32042336, 2020). "For example, in glioblastoma (GBM) and melanoma, EZH2 mediates the lysine methylation of STAT3, leading to its activation, which enhances tumorigenicity." (PMID 32448308, 2020). "EZH2 is often dysregulated in melanoma, the deadliest skin cancer, and it has been shown to interact with DNMT and cause hypermethylation of TSG promoters, resulting in silencing of TSGs." (PMID 32751889, 2020). "The aim of this study is to evaluate expression patterns and the predictive value of H3K27me3 and EZH2 in metastatic melanoma samples prior to ICB." (PMID 32041674, 2020). "Percentage of H3K27me3 positive melanoma cells was significantly correlated with percentage of EZH2 positive melanoma cells (ρ = .445, p = .002)." (PMID 32041674, 2020). "Nonetheless, all three studies concluded that EZH2 is an oncogenic protein of significance in melanoma that promotes melanoma initiation and progression." (PMID 33024276, 2020). "EZH2 and H3K27me3 expression has also been linked to a dedifferentiated, epithelial-mesenchymal transformation (EMT) like melanoma phenotype." (PMID 32041674, 2020). "In consent with these findings, our results showed that inhibition of CDKN1C by EZH2 leads to a significant increase in melanoma cell viability and a decrease in oxidative stress and apoptosis due to catalyzing the H3K27 trimethylation." (PMID 32308561, 2020). "Functional experiments showed that knockdown of ILF3-AS1 inhibits melanoma cell proliferation, migration, and invasion through interacting with EZH2 to represses miR-200b/a/429 expression." (PMID 32117452, 2020). "A more recent study showed that EZH2 plays an important role in melanoma genesis and metastasis by silencing genes that are necessary for the integrity of primary cilia." (PMID 33024276, 2020). "Our findings indicate that further studies should perform paired histopathological and molecular analyses to better understand EZH2 and H3K27me3 expression in melanoma." (PMID 32041674, 2020). "In the group of the non-responders (20/44, progressive disease (PD)), 13/20 (65.0%) showed H3K27me3 expression and 2/20 (10%) showed EZH2 expression of the melanoma cells." (PMID 32041674, 2020). "Analysis of a panel of melanoma cell lines indicated co-expression of NFATc2 and of EZH2, thus supporting the rationale for testing the potential anti-tumor effects of pharmacological co-targeting." (PMID 30710146, 2019). "Metabolomics profiling of melanoma has demonstrated the role of EZH2 in the suppression of oxidative pathways and increased glycolytic activity." (PMID 30089854, 2019). "In late stage prostate tumors, EZH2 upregulation is related to gene amplification, whereas its expression is profoundly affected by the BRAF (V600E) mutation in melanoma." (PMID 31921860, 2019). "In agreement, targeting of FOXM1 and of EZH2, as well as of the upstream regulator c-Myc, induced a reversal of the EMT-like profile of melanoma cells, associated with upregulation of MITF and inhibited melanoma migratory and invasive activity." (PMID 30710146, 2019). "In conclusion, LINC-PINT inhibits the tumorigenicity of melanoma through recruiting EZH2 to the promoter of its target genes, leading to H3K27 trimethylation and epigenetic silencing of target genes." (PMID 31921860, 2019).
melanoma (continued). "Crucially, pharmacological co-targeting of NFATc2 and EZH2 exerted significant anti-tumor activity not only against BRAF-mutant melanomas with intrinsic resistance to BRAF inhibitors, but even against NRAS-mutant and BRAF/NRAS wild type melanoma cells." (PMID 30710146, 2019). "Pharmacological co-targeting of NFATc2 and EZH2 exerted significant anti-tumor effects in distinct melanoma subsets, including BRAF-mutant but BRAF-inhibitor-resistant cell lines, as well as NRAS mutant and BRAF/NRAS wild-type tumors." (PMID 30710146, 2019). "The fact that EZH2 as downstream factor of CDK6 was shown to regulate angiogenesis in melanoma indicates that additional angiogenic factors are involved in the CDK6 mediated angiogenesis program." (PMID 30858922, 2019). "In summary, we identified an lncRNA, LINC-PINT, and proposed a mechanistic model to elucidate its role in the regulation of melanoma progression through EZH2-mediated epigenetic silencing." (PMID 31921860, 2019). "In NFATc2+ EZH2+ melanoma cell lines pharmacological co-targeting of NFATc2 and EZH2 exerted strong anti-proliferative and pro-apoptotic activity, irrespective of BRAF or NRAS mutations and of BRAF inhibitor resistance." (PMID 30710146, 2019). "It is demonstrated that EZH2 is mainly upregulated in solid tumors, melanoma included, which indicates a more aggressive tumor growing pattern and poorer prognosis in most cases." (PMID 31921860, 2019). "Collectively, these results support a model where an NFATc2/c-Myc/FOXM1/EZH2 axis regulates the EMT-like/invasive program of melanoma cells." (PMID 30710146, 2019). "The importance of chromatin remodelling deregulation in melanoma brought to investigate EZH2 inhibitors in EZH2-enriched tumors reveals promising pre-clinical activities." (PMID 31861757, 2019). "Here, we revealed a novel transcript of LINC-PINT as a tumor suppressor to inhibit melanoma progression via recruiting EZH2 to the promoter of cell cycle related genes." (PMID 31921860, 2019). "miRNA-32, miR-137 and miR-506 also directly target EZH2 transcript and suppress tumor proliferation, angiogenesis and metastasis in melanoma, colon cancer and glioblastoma." (PMID 29556394, 2018). "High levels of EZH2 activation are observed in neuroblastoma, hepatocellular carcinoma, small cell lung cancer, and melanoma." (PMID 30466474, 2018). "PDCD4, a tumor suppressor, was recently demonstrated to be negatively regulated by CASC15, via recruiting EZH2 and subsequently changing H3 K27me3 level in melanoma." (PMID 30519392, 2018). "Altogether, our data suggested that the coexistence of EZH2 gain and the BRAF V600E mutation was prevalent in melanoma, especially mucosal subtype." (PMID 29202777, 2017). "EZH2 and MITF, in fact, are targets of miR-101 and miR-137 that have been associated with the control of the invasive phenotype of melanoma cell lines." (PMID 29112174, 2017). "E2F transcription factors including their main representative E2F1 are upstream regulators of the epigenetic polycomb complex around EZH2 constituting an important link to maintenance of the stem cell-like state of melanoma cells." (PMID 28265786, 2017). "Accordingly the EZH2 inhibitor GSK343 was used to assess the contribution of EZH2 to NFIB driven melanoma cell migration in the A2058− NFIB and MM96L− NFIB cells." (PMID 28119061, 2017). "miR-200b/a/429 is a well-known EZH2 target gene, which also has crucial roles in the proliferation, migration, and invasion of melanoma cells." (PMID 28935763, 2017). "Recent intravital imaging studies have found that EZH2 marks a heterogeneous, highly motile subpopulation of cells within melanoma tumours that is thought to promote early stages of metastasis." (PMID 28119061, 2017). "Next, we analyzed the prognostic significance of EZH2 gain for overall survival (OS) and disease-free survival (DFS) in melanoma patients harbouring BRAF V600E mutation." (PMID 29202777, 2017).